USP13 (ubiquitin specific peptidase 13)
Diseases named in the same sentence as USP13 in open-access papers (continued):
Sharing a sentence is not in itself a finding about the gene and the disease.
prostate carcinoma (continued). "We also observed a positive correlation between the expression of USP13 and DDR genes in prostate cancer samples." (PMID 36564767, 2022). "USP13 staining was scored as grade 0 (negative), 1 (weak), 2 (moderate), or 3 (strong) in 242 prostate cancer tissues and 22 adjacent non-neoplastic control tissues." (PMID 42195268, 2026). "Higher USP13 grades were exhibited by adjacent non-neoplastic tissues than prostate carcinoma." (PMID 42195268, 2026). "For this, the study focused on assess three embryonal CNS tumor lineages (DAOY, USP13-MED and USP7-ATRT), as well as three non-CNS tumor cell lines from breast, colorectal and prostate cancer." (PMID 39347716, 2024).
glioma (5 papers, 2020 to 2025). A benign or malignant brain and spinal cord tumor that arises from glial cells (astrocytes, oligodendrocytes, ependymal cells). "As a highly expressed protein in glioma stem cells (GSCs), USP13 maintains GSC self-renewal abilities by stabilizing the critical transcription factor c-Myc." (PMID 35898882, 2022). "Moreover, USP13 depletion represses the proliferation of glioma stem cells (GSCs) and restrains tumor growth in mice." (PMID 33195243, 2020). "The phosphorylation of USP13 at Tyrosine 708 by CLK3 is required for USP13′s binding to c-Myc, which prevents its Fbxl14-mediated ubiquitination of c-Myc in glioma stem cells." (PMID 36612196, 2022).
non-small cell lung carcinoma (5 papers, 2022 to 2025). A group of at least three distinct histological types of lung cancer, including non-small cell squamous cell carcinoma, adenocarcinoma, and large cell carcinoma. "USP13 expression is driven by oncogenic KRASG12C in non-small cell lung cancer (NSCLC) through Ras-responsive element-binding protein 1 (RREB1)." (PMID 41307804, 2025). "For example, in non-small-cell lung cancer, downregulation of USP13 suppresses ATK/MAPK signaling, reducing c-Myc protein levels and retards tumor growth both in tumor cells and nude mice." (PMID 35445009, 2022). "This genomic amplification of USP13 has been identified in other human cancers, including esophageal squamous cell carcinoma (29.5% Amp), head and neck squamous cell carcinoma (15.1% Amp), endometrium carcinoma (8.8% Amp), and non-small cell lung cancer (18.1% Amp)." (PMID 35173307, 2022). "For instance, in non-small-cell lung cancer (NSCLC), downregulation of USP13 inhibits MAPK/AKT signaling." (PMID 35445009, 2022).
ovarian tumor (5 papers, 2016 to 2022). "Another important function of USP13 is that it promotes the DNA damage response in ovarian tumor cells by recruiting the BRCA1/RAP80 complex to DNA damage sites." (PMID 36564767, 2022). "Similar to MCL1, USP13 is genomically amplified in a variety of human cancers and ubiquitously overexpressed in lung and ovarian tumor specimens." (PMID 29335437, 2018). "Aberrant overexpression of USP13 in ovarian tumours was also confirmed by western blot using normal and tumour tissue samples." (PMID 27892457, 2016). "USP13 expression is markedly increased in advanced ovarian tumours and is significantly correlated with tumour grade." (PMID 27892457, 2016). "Inhibiting USP13 remarkably suppresses ovarian tumour progression and sensitizes tumour cells to the treatment of PI3K/AKT inhibitor." (PMID 27892457, 2016). "Our findings suggest that USP13 amplification is likely an important driver in ovarian tumour progression." (PMID 27892457, 2016). "USP13 mRNA expression is increased in advanced ovarian tumors and correlates with tumor grade." (PMID 35173307, 2022). "Notably, USP13 greatly enhanced peritoneal metastasis of ovarian tumors with frequent development of hemorrhagic ascites." (PMID 35173307, 2022). "Moreover, lower metastatic activity of the USP13-depleted ovarian tumours was observed in common metastatic sites (mesentery, omentum, diaphragm, peritoneal wall, perihepatic site, pelvic and kidney) of HGSC." (PMID 27892457, 2016). "Next, we determined whether inhibition of USP13 sensitizes ovarian tumours to the treatment of the pan-AKT inhibitor MK-2206 in vivo." (PMID 27892457, 2016). "Depletion of USP13 resulted in profound decrease in tumour weight and number of tumour nodules in both CAOV3- and HeyA8-derived ovarian tumour xenografts." (PMID 27892457, 2016). "To determine the positive correlation between USP13 and ACLY/OGDH levels in clinical ovarian tumours, we examined their levels using a tumour tissue microarray including 72 clinical ovarian tumour samples." (PMID 27892457, 2016). "USP13 and MCL1 display increased copy numbers in many TCGA (The Cancer Genome Atlas) cancer types, and are correlatively upregulated only at protein level in lung and ovarian tumor specimens." (PMID 29335437, 2018). "Third, USP13 and MCL1 were similarly amplified and overexpressed in lung and ovarian tumors." (PMID 29335437, 2018).
bladder cancer (4 papers, 2019 to 2025). "Here, we reported that NF-kB/miR-130b/301b cluster axis promoted loss of PTEN expression by decreasing USP13 expression and enhanced progression of bladder cancer." (PMID 31200745, 2019). "Furthermore, we found decreased expression level of USP13 is associated with an increased risk of progression to BC, suggesting a tumor suppressor role of USP13 in bladder cancer." (PMID 31200745, 2019). "In contrast, USP13 inhibits the progression of bladder cancer by enhancing PTEN expression, which is regulated by NF-κB." (PMID 40746889, 2025). "Some studies indicate that USP13 inhibits AKT by stabilizing PTEN in bladder cancer, thereby reducing tumor proliferation, invasion, and migration." (PMID 40746889, 2025). "To study the biological function of USP13 in bladder cancer, we overexpressed USP13 by transducing the BC cells with lentivirus vector encoding USP13." (PMID 31200745, 2019). "USP13 overexpression alone doesn’t affect cell proliferation and invasion of bladder cancer cell line." (PMID 31200745, 2019). "We found that loss of USP13 led to the downregulation of PTEN and promoted proliferative, invasive and migrative capacities of bladder cancer cells." (PMID 31200745, 2019). "To investigate the regulatory role of USP13 in BC, we detected mRNA expression of USP13 in a cohort of 50 pairs of bladder cancer tissues and matched normal bladder mucosa tissues." (PMID 31200745, 2019). "USP13 has been reported to be involved in the tumorigenesis of human cancers, however, its functional role and regulatory mechanisms in bladder cancer (BC) remain unclear." (PMID 31200745, 2019). "In bladder cancer, miR-301b-3p downregulates USP13 to further lower the level of tumor suppressor PTEN, contributing to bladder cancer occurrence." (PMID 39525474, 2024). "Our present study reveals that USP13 functions as a tumor suppressor by interacting with PTEN protein and increasing its expression in bladder cancer." (PMID 31200745, 2019). "We reported a potential regulatory loop that the NF-kB-induced miR-130b/301b overexpression decreased USP13 expression and subsequently resulted in the downregulation of PTEN protein and promoted tumorigenesis of bladder cancer." (PMID 31200745, 2019). "Although mounting studies suggest the oncogenic or tumor suppressor role of USP13 is context-dependent, however, its biological function in bladder cancer has not been reported yet." (PMID 31200745, 2019).
colorectal cancer (4 papers, 2016 to 2025). A primary or metastatic malignant neoplasm that affects the colon or rectum. "The deubiquitinase ubiquitin-specific protease 13 (USP13) has been implicated in various cancers, yet its precise molecular function and clinical significance in colorectal cancer (CRC) remain poorly defined." (PMID 41307804, 2025). "Our analysis of cancer genomics reveals that the USP13 gene is frequently amplified in human OVCA, but not in breast and colorectal cancers, suggesting that the role of USP13 in oncogenesis is context-dependent." (PMID 27892457, 2016).
lung fibrosis (4 papers, 2015 to 2025). "For instance, USP13 acts as a protective factor in age-related PF, with the age-mediated depletion of USP13 promoting lung fibrosis through Beclin 1 deubiquitination." (PMID 40225577, 2025). "The results of this study revealed that the decrease of TXNIP in lungs apparently contributes to the pathogenesis of pulmonary fibrosis and that USP13 can target TXNP for deubiquitination and regulate its stability." (PMID 38529321, 2024). "In pathology, it has been reported that USP13 is important in the pathogenesis of infection, inflammation, idiopathic pulmonary fibrosis (IPF), neurodegenerative diseases, and cancers." (PMID 36188217, 2022). "Besides lung fibrosis, liver and kidney fibrosis are also common clinical diseases, and the function of USP13 in these diseases remains to be explored." (PMID 36188217, 2022). "Thus, USP13 may be a novel potential target for intervention in lung fibrosis." (PMID 26453058, 2015).
lung squamous cell carcinoma (4 papers, 2016 to 2025). "Among the 20 candidate MCL1-regulating DUBs, USP13 drew our attention because it was amplified in several types of human cancer, particularly in 45.9% of lung squamous cell carcinoma (504 samples) and 28% of ovarian serous adenocarcinoma (603 samples)." (PMID 29335437, 2018). "However, USP13 gene is amplified in several types of human cancer, particularly in 52% of lung squamous cell carcinoma and 29.3% of HGSC." (PMID 27892457, 2016). "Copy number analysis of TCGA tumor samples in cBioportal database showed that both USP13 and MCL1 were genomically amplified in a wide range of cancer types, in particular a considerable proportion of lung adenocarcinoma, lung squamous cell carcinoma and ovarian serous carcinoma cases." (PMID 29335437, 2018).
Alzheimer disease (3 papers, 2021 to 2025). A progressive, neurodegenerative disease characterized by loss of function and death of nerve cells in several areas of the brain leading to loss of cognitive function such as memory and language. "USP13 is upregulated in Alzheimer’s disease (AD) and Parkinson’s disease (PD), and USP13 knockdown via shRNA reduces neurotoxic proteins and increases proteasome activity in models of neurodegeneration." (PMID 34564439, 2021). "USP13 was identified as a downstream effector of TDP-43, a protein implicated in several neurodegenerative disorders including amyotrophic lateral sclerosis (ALS), frontotemporal dementia (FTD), and Alzheimer’s disease (AD)." (PMID 40933192, 2025).
gastric cancer (3 papers, 2022 to 2023). A primary or metastatic malignant neoplasm involving the stomach. "In gastric cancer, the high expression of USP13 is associated with high invasion, contributing to reduced survival rate of patients." (PMID 35445009, 2022). "It is supposed that USP13 deubiquitinated and stabilized Snail protein, promoting metastasis in gastric cancer cells." (PMID 35445009, 2022). "In this study, we investigated the gastric cancer (GC) data from the TCGA and GEO databases and found that ubiquitin-specific protease USP13 was significantly up-regulated in GC samples." (PMID 37311811, 2023).
gastrointestinal stromal tumor (3 papers, 2023 to 2025). "For example, METTL3-mediated stabilization of USP13 RNA has been shown to promote autophagy and imatinib resistance in gastrointestinal stromal tumors, while in HCC, METTL3 has been reported to regulate cancer stem cell properties and contribute to lenvatinib resistance via FZD10." (PMID 39472692, 2025). "On the contrary, in gastrointestinal stromal tumors, IGF2BP2 stabilizes the deubiquitinase ubiquitin-specific peptidase 13 (USP13), which extends the half-life of autophagy-related protein 5 (ATG5)." (PMID 39596216, 2024).
lung adenocarcinoma (3 papers, 2018 to 2025). A carcinoma that arises from the lung and is characterized by the presence of malignant glandular epithelial cells. "A recent study revealed that USP13 interacts with and catalyzes the deubiquitination of the transcription factor NFE2L2 and promotes an autophagy-to-ferroptosis switch in KRAS mutant lung adenocarcinoma." (PMID 41330897, 2025). "Moreover, the USP13-mediated deubiquitination process directly upregulated MYC protein levels with increased expression of SOX2 and squamous features in KP mouse and human lung adenocarcinoma cells." (PMID 38093367, 2023).
medulloblastoma (3 papers, 2023 to 2025). A malignant, invasive embryonal neoplasm arising from the cerebellum. "Following ZIKV infection, we observe distinct sub-cellular staining for ZIKV NS2B from 12 hpi in the aggressive paediatric USP7 ATRT and USP13 medulloblastoma cell lines." (PMID 40240536, 2025). "The DAOY cell line, representative of the Sonic Hedgehog (SHH) subgroup, and the USP13-Med cell line, which was obtained from a 3-year-old boy with classic medulloblastoma, subgroup 422." (PMID 37945695, 2023). "Employing an in silico approach, we sought to model how the ZIKV-induced pro-inflammatory USP13 medulloblastoma secretome may interact with tumour and immune cells of the medulloblastoma TME." (PMID 40240536, 2025).
Sepsis (3 papers, 2023 to 2025). Sepsis is defined as life-threatening organ dysfunction caused by a dysregulated host response to infection. "miR-19a-3p has been shown to suppress USP13 expression in sepsis-induced ALI, resulting in increased cytokine production in alveolar macrophages." (PMID 40413349, 2025). "Inhibition of miR-19a-3p reduced sepsis-mediated lung injury through upregulation of USP13 expression." (PMID 37359559, 2023). "USP13 inhibited sepsis-induced inflammation and cardiomyocyte oxidative stress via induction of nuclear factor erythroid 2-related factor 2 (Nrf2)." (PMID 37359559, 2023). "Besides, USP13 inhibits the LPS-induced production of multiple inflammatory cytokines by deubiquitinating and inactivating IRAK4 and thus negatively regulates LPS-induced mouse sepsis shock." (PMID 41004574, 2025).
serous ovarian cancer (3 papers, 2016 to 2020). "The USP13 gene is co-amplified with PIK3CA in 29.3% of high-grade serous ovarian cancers and its overexpression is significantly associated with poor clinical outcome." (PMID 27892457, 2016). "USP13 is co-amplified with PIK3CA in high-grade serous ovarian cancer." (PMID 32974170, 2020).
small cell lung carcinoma (3 papers, 2022 to 2025). Small cell lung cancer (SCLC) is a highly aggressive malignant neoplasm, accounting for 10-15% of lung cancer cases, characterized byrapid growth, and early metastasis. "In small cell lung cancer, USP13 is highly expressed and is associated with poor prognosis." (PMID 40621620, 2025). "Besides ACLY and OGDH, fatty acid synthase (FASN) was recently identified as a novel substrate of USP13 in small cell lung cancer (SCLC)." (PMID 36188217, 2022).
viral infection (3 papers, 2011 to 2023). "Mechanistically, viral infection strengthens the cooperation of Usp22 with another deubiquitinase Usp13 that promotes cleavage of the stimulator of interferon genes protein (STRING)." (PMID 37896966, 2023). "To gain insight into the function of USP13 in host defence against viral infection in vivo, we monitored survival of Usp13+/+ and Usp13m/m mice after intravenous (i.v.)injection of HSV-1." (PMID 28534493, 2017). "It was reported that the mRNA level of USP13 is increased in thyroid tumor pathologies, and the activity of USP13 is up-regulated by mitogen activation or virus infection." (PMID 22216260, 2011). "The basal ubiquitination of STING was increased in USP13-knockdown THP-1 cells or in USP13 deficient BMDCs or MEFs compared to the controls without viral infection." (PMID 28534493, 2017). "Indeed, HSV-1-induced activation of IRF3 and NF-κB and subsequent induction of downstream genes were enhanced in USP13 deficient mouse cells or in USP13-knockdown THP-1 cells, suggesting that the residual USP13-STING association restricts excessive activation of STING in response to viral infection." (PMID 28534493, 2017). "Taken together, these data suggest that USP13 targets STING for deubiquitination in the presence or absence of viral infection." (PMID 28534493, 2017). "Results from endogenous immunoprecipitation and immunoblot analysis revealed that USP13 constitutively interacted with STING without viral infection in mouse bone marrow-derived dendritic cells (BMDCs) and mouse embryonic fibroblasts (MEFs)." (PMID 28534493, 2017).
clear cell renal cell carcinoma (2 papers, 2022 to 2023). "Protein expression of USP13 was found to be downregulated in tumor tissues compared with normal tissue samples in pancreatic adenocarcinoma (PAAD) (C), head and neck squamous carcinoma (HNSC) (D), clear cell renal carcinoma (ccRCC) (E) and uterine corpus endometrial carcinoma (UCEC) (F) by UALCAN." (PMID 36564767, 2022). "The results suggested that the protein expression of USP13 is significantly elevated in tumor tissues compared with normal samples in pancreatic adenocarcinoma (PAAD), head and neck squamous carcinoma (HNSC), clear cell renal cell carcinoma (ccRCC) and uterine corpus endometrial carcinoma (UCEC)." (PMID 36564767, 2022).